MTHFSD (methenyltetrahydrofolate synthetase domain containing)
Synonyms: FLJ12998
Tractability: PROTAC: ubiquitination databases record sites on it; its protein half-life has been measured.
Gene: Protein-coding gene on chromosome 16 (86,530,178 to 86,555,235, reverse strand). Ensembl gene ENSG00000103248.
Subcellular location (Human Protein Atlas): Nucleoplasm; Vesicles
Gene Ontology:
Molecular function: RNA binding; nucleic acid binding
Genetic constraint (gnomAD): Loss-of-function variants: 31 observed, 26.34 expected, observed/expected ratio (o/e) 1.18, 90% interval 0.88 to 1.59. The upper end of that interval is the gene's LOEUF score, 1.59, which puts it in group 6 of 6, group 1 being the genes least tolerant of losing a copy. Missense variants: 529 observed, 379.55 expected, observed/expected ratio (o/e) 1.39, 90% interval 1.3 to 1.5. Synonymous variants: 160 observed, 145.55 expected, observed/expected ratio (o/e) 1.1, 90% interval 0.97 to 1.25.
Homologues: Orthologues: chimpanzee MTHFSD (91% identical), macaque MTHFSD (84% identical), rat Mthfsd (75% identical), pig MTHFSD (70% identical), mouse Mthfsd (70% identical), rabbit MTHFSD (63% identical), tropical clawed frog mthfsd (62% identical), guinea pig MTHFSD (59% identical), zebrafish mthfsd (52% identical), dog MTHFSD (35% identical), Drosophila melanogaster lost (31% identical).
Diseases named in the same sentence as MTHFSD in open-access papers:
MTHFSD is named in the same sentence as 6 diseases in open-access papers, as found by Europe PMC text mining. Sharing a sentence is not in itself a finding about the gene and the disease. The quoted sentences say what the papers report.
asthma (1 paper, 2025). "We visualized the top three significant CpG sites: chr16:86536881 (MTHFSD), chr2:10529804, and chr3:59456728 (CFAP20DC-DT), exhibiting the largest effect sizes which demonstrated consistency across both amnion and nasal tissues in relation to maternal asthma history." (PMID 41256158, 2025).
psychosis (1 paper, 2025). "A 2016 study on methamphetamine-associated psychosis (MAP) identified MTHFSD as a candidate biomarker for RNA degradation, highlighting its role in folate catabolism and methionine metabolism." (PMID 40142297, 2025).
cancer (2 papers, 2024 to 2025). A tumor composed of atypical neoplastic, often pleomorphic cells that invade other tissues. "The Methenyltetrahydrofolate Synthetase-Domain-Containing (MTHFSD) gene plays a pivotal role in diverse physiological processes, including vascular health and cancer susceptibility, through its cytoplasmic activity in RNA binding, which facilitates crucial cellular functions." (PMID 40142297, 2025).
MTHFSD also shares sentences with these, for which no sentence is quoted: alveolar capillary dysplasia (1 paper); bipolar disorder (1); congenital heart malformation (1).